HEXD-IT1 (HEXD intronic transcript 1)
Synonyms: formerly HEXDC-IT1
Gene: Long non-coding RNA gene on chromosome 17 (82,425,498 to 82,427,310, forward strand). Ensembl gene ENSG00000279066.
Diseases named in the same sentence as HEXD-IT1 in open-access papers:
HEXD-IT1 is named in the same sentence as 1 disease in open-access papers, as found by Europe PMC text mining. Sharing a sentence is not in itself a finding about the gene and the disease. The quoted sentences say what the papers report.
depression (1 paper, 2025). "From the pool of identified genes, CHN1 and HEXD-IT1 emerged as upregulated in AD patients with comorbid depression, whereas CXCR6 was pinpointed as a downregulated gene." (PMID 41333466, 2025).